NOTCH3 (notch receptor 3)
Diseases named in the same sentence as NOTCH3 in open-access papers (continued):
Sharing a sentence is not in itself a finding about the gene and the disease.
ovarian carcinoma (continued). "We then investigated the relationship between Notch3 and IL-8 levels in patients diagnosed with ovarian cancer by examining the level of IL-8 in the ascites by ELISA and the expression of Nocth3 in tumor tissue samples from 12 ovarian cancer patients by immunohistochemical staining." (PMID 34277625, 2021). "In addition, investigators testified that miR-136 introduction contributed to the sensitivity of ovarian cancer to PTX by binding to notch receptor 3 (NOTCH3)." (PMID 34649611, 2021). "Collectively, IL-8 secreted from CAFs and cancer cells promotes stemness in human ovarian cancer via the activation of the Notch3-mediated signaling, which may provide a novel strategy for ovarian cancer treatment." (PMID 34277625, 2021). "Illustrating this, carboplatin-induced ERK phosphorylation and apoptosis could be inhibited by Notch3 activation in some ovarian cancer cells." (PMID 34680255, 2021). "Consequently, overexpression of Notch3 leads to the expansion of CSCs, resulting in increased resistance against platinum in ovarian cancer." (PMID 33968932, 2021). "Additionally, increased expression of Notch3 has correlated with poor prognosis in patients with ovarian cancer." (PMID 32776013, 2020). "In addition, NOTCH3 overexpression is related to the recurrence of ovarian cancer, poor prognosis, and resistance to carboplatin." (PMID 33316986, 2020). "Our results strongly suggest that integrin dimer α1β1 is a key downstream factor in Notch3-induced metastasis, and targeting this complex may reduce metastasis in both Notch3-induced and Notch3-independent ovarian cancers." (PMID 32525899, 2020). "Knockdown of c-Kit reduced the levels of phospho-PHB and Notch3 in metastatic ovarian cancer cells." (PMID 32169072, 2020). "Notch3 expression in early stage ovarian cancers may increase the likelihood of progression to metastatic later stage cancers." (PMID 32525899, 2020). "Interestingly, reduced Notch3 endocytic turnover has also been shown to play a role in stimulating Notch3 activity in ovarian cancer cells." (PMID 32210034, 2020). "Both ZIP4 and NOTCH3 play important roles in tumor development in ovarian cancer." (PMID 33316986, 2020). "Further study of other Notch3 targets may elucidate other important mechanisms of ovarian cancer progression." (PMID 32525899, 2020). "A previous study reported that Notch3 protein levels are elevated in recurrent tumor tissues, compared with primary tumor tissues from same patients, and that increased Notch3 expression is significantly correlated with poor clinical outcomes in ovarian cancer patients." (PMID 31261739, 2019). "However, Notch 3 overexpression blocked this anti-proliferative effect of SIRT6 in ovarian cancer cells." (PMID 31591350, 2019). "In the majority of patients with recurrent HGS ovarian cancer, Notch3 is overexpressed." (PMID 30042330, 2018). "In HGS ovarian cancer, Notch3 expression is amplified/overexpressed." (PMID 30042330, 2018). "Those expressing high Notch3 levels had decreased overall survival (22 vs. 37 months) and decreased progression-free survival (3 vs. 8 months) suggesting that Notch3 expression is a factor in the recurrence of ovarian cancer as well as a prognostic indicator in recurrent disease." (PMID 30042330, 2018). "However, Notch3 mRNA high expression was significantly correlated to favorite PFS for all ovarian cancer patients, HR 0.78 (0.68–0.89), p = 0.00026." (PMID 28415574, 2017). "In addition, Notch3 RNA transcript and protein are highly expressed in ovarian carcinomas and its elevated expression correlates with resistance to chemotherapy and decreased survival." (PMID 29069826, 2017). "Inhibition of Notch3 inhibited ovarian cancer growth and induced apoptosis." (PMID 28415574, 2017). "This leads to the hypothesis that Notch3 pathway inhibition in ovarian cancer could produce the most robust effects in a PTX-resistant tumor." (PMID 29069826, 2017).
ovarian carcinoma (continued). "Given that Notch3 signaling supports CSC activity in ovarian cancer, inhibition of the Notch3 signaling could selectively target tumor-initiating populations and act to restore chemosensitivity." (PMID 29069826, 2017). "In a previous study, overexpression of NOTCH3 in ovarian cancer cells promoted expansion of CSCs, and treatment with γ–secretase inhibitor resulted in depletion of CSCs with increased sensitivity to platinum drug and decreased expression of stemness-related gene expression." (PMID 27489349, 2016). "Therefore, the combined assessment of Notch3 and pS6 expression is a better choice of prognostic biomarker for overall survival in ovarian epithelial cancer than Notch3 or pS6 alone." (PMID 27445438, 2016). "Notch3 amplification was observed in ovarian cancer and is required for tumor proliferation." (PMID 28036048, 2016). "Previous studies have shown that NOTCH3 is overexpressed in the tumor cells of various types of cancers, including non-small cell lung cancers, pancreatic cancers, colorectal cancers and ovarian cancers, and that such overexpression correlates with poor prognosis of the patients." (PMID 27124156, 2016). "A recent study showed that NOTCH3 gene is significantly overexpressed in ovarian cancer samples." (PMID 25738469, 2015). "Results from the present study demonstrate that MSeA can synergistically enhance the efficacy of carboplatin in the killing of OVCA429/NICD3 ovarian cancer cells, suggesting a new strategy to treatment of high grade ovarian carcinoma exhibiting Notch3 activation." (PMID 25010594, 2014). "Although Notch hyperactivity has been observed in many types of cancers, the interactome of Notch receptor remains largely unknown, especially for Notch3, which is involved in ovarian cancer pathogenesis." (PMID 25356737, 2014). "Because ROS are also implicated in Notch3 signaling pathway, we tested the hypothesis that MSeA could repress the desensitization of OVCA429/NICD3 ovarian cancer cells to carboplatin." (PMID 25010594, 2014). "In a study of Notch ligands, Jag1 was shown to be the most highly expressed ligand in both ovarian cancer cells and surrounding peritoneal mesothelial cells with interaction of Jag1 and Notch3 resulting in activation of the signaling cascade and promotion of cell proliferation and adhesion." (PMID 25366565, 2014). "Finally, the natural compounds xanthohumol and withaferin A inhibited cell growth and induced apoptosis and cell cycle arrest in ovarian cancer cell lines through downregulation of Notch1 (withaferin A and xanthohumol) and Notch3 (withaferin A)." (PMID 25366565, 2014). "In addition, Pbx1 and DLGAP5 have been identified as direct target genes of Notch3 in ovarian cancer, and knockdown of either target with shRNAs led to reduced cell proliferation and, in the case of Pbx1 knockdown, impaired tumor formation." (PMID 25366565, 2014). "Moreover, elevated nuclear Notch3 immunostaining has been found in recurrent serous ovarian carcinoma specimens as compared to primary ovarian cancer samples from the same patients." (PMID 25366565, 2014). "Moreover, NOTCH3 amplifications in other cancers such as non-small cell lung cancer, ovarian cancer and T-cell leukemia have also been found." (PMID 24143218, 2013). "To demonstrate whether Notch3 signaling is essential for Jagged1 expression, we compared Jagged1 mRNA and protein levels between ovarian cancer cells transfected with Notch3 specific shRNAs and control shRNA." (PMID 20953350, 2010). "Both mechanisms may sustain Notch3 signaling in ovarian cancer cells and contribute to the pathogenesis of ovarian carcinoma." (PMID 20953350, 2010). "Based on our previous studies, we hypothesized that cell-cell contacts between adjacent ovarian cancer cells elicit Notch3 signaling which in turn upregulates its ligand, Jagged1, thus maintaining long-term Notch3 signaling in cancer cells." (PMID 20953350, 2010).
ovarian carcinoma (continued). "While not specifically studied in MCs, a connection with KIT, the principal receptor tyrosine kinase of MCs, was recently reported, whereby KIT activation in ovarian cancer stem cells could stabilize Notch Receptor 3 (NOTCH3) and thereby increase the downstream target PBX1." (PMID 36142795, 2022). "In the present study, we found that IL-8 derived from CAFs could promote angiogenesis and proliferation of NFs through the activation of the AKT and ERK pathways and could induce the stemness and malignant proliferation of ovarian cancer cells through the Notch3-mediated signaling." (PMID 34277625, 2021). "Finally, we explored the critical role of Notch3 in the survival of patients with ovarian cancer." (PMID 34277625, 2021). "Our data show that in ovarian tumor microenvironment, IL-8 derived from cancer cells and CAFs promotes the proliferation and stemness of cancer cells through the Notch3 signaling pathway, suggesting that the IL-8/Notch3 signaling may be a potential target for ovarian cancer treatment in the future." (PMID 34277625, 2021). "Our results suggest that Notch3 plays an important role in the early stages of ovarian metastasis, and thus inhibition of Notch3 signaling may provide clinical benefit in prevention of progression of ovarian cancer from low-burden to high-volume dissemination." (PMID 32525899, 2020). "Therefore, we hypothesized that the inhibition of Notch3 using modulation of miRNAs in PTX-resistant ovarian cancer cells may result in sensitizing the PTX resistant ovarian cancer cells, and inducing inhibition of cellular proliferation and cancer cell death." (PMID 29069826, 2017). "Similarly, amplification of NOTCH3 has been described in ovarian cancers." (PMID 23825651, 2013). "Moreover, we found that in ovarian cancer cells, Notch3 could be co-immunoprecipitated with Jagged1, and ectopic expression of NICD3 could partly rescue the growth-inhibitory effect produced by Jagged1 withdrawal." (PMID 20953350, 2010). "Jagged1 is a transcriptional target of both Notch3-ICD and β-catenin, and both pathways can sustain Notch3 signaling and promote ovarian carcinoma progression by supporting tumor cell adhesion and growth." (PMID 41294868, 2025). "Contrarily, a synergistic or additive effect of the MAP4K4i and both RG-4733 and DAPT, GSIs on Notch3 expression was detected in OVCAR-3 and the primary ovarian carcinoma cells OC236." (PMID 39592661, 2024). "The activation of Notch3 is not limited to COMP but can also be achieved by other TSP family members, such as TSP2 function in lung and ovarian cancer cells." (PMID 38615020, 2024). "Notch2/Notch3 and other NOTCH signaling molecules have achieved certain effects by inhibiting Jag1 in a mouse ovarian cancer model." (PMID 35332121, 2022). "This potential interplay of Notch3 along with p21 and VEGFA evidently emerges as critical regulators during tumor metastasis leading to the progression of ovarian carcinoma." (PMID 35884426, 2022). "In our study, the c-Kit-mediated upregulation of cancer stemness-related Notch3—PBX1 and β-catenin—ABCG2 signaling pathways and promotion of ovarian cancer tumorigenicity and drug resistance were all phospho-PHBY259 dependent." (PMID 32169072, 2020). "We have previously demonstrated that Notch3-specific inhibition by Notch3 specific siRNA and γ-secretase inhibitor (GSI) sensitizes PTX-resistant ovarian cancer cells to paclitaxel treatment." (PMID 29069826, 2017). "Our previous studies also demonstrated that Notch3 overexpression was induced by long-term use of PTX and acquisition of PTX-resistance in ovarian cancer cells." (PMID 29069826, 2017). "In the current study, we found that miR-150 targets Notch3, and that the artificial overexpression of miR-150 enhanced PTX sensitivity in PTX-resistant ovarian cancer cells by inhibiting proliferation and promoting apoptosis." (PMID 29069826, 2017).
ovarian carcinoma (continued). "There was a significantly higher Notch3 to WWP2 protein expression ratio than the normal epithelial cells in ovarian cancer tissues, primary cultures of ovarian cancer cells, and ovarian cancer cell lines." (PMID 25356737, 2014). "When expression levels of Notch3 was plotted against WWP2 expression levels in ovarian cancer tissues and primary cultures, an inverse correlation in protein expression levels between WWP2 and Notch3 was observed." (PMID 25356737, 2014). "To determine if WWP2 interacted with endogenous Notch3 fragments, we ectopically expressed WWP2-FLAG in OVCAR3 cells because WWP2 expression is relatively low in most tested ovarian cancer cell lines." (PMID 25356737, 2014). "Overexpression of NICD3 significantly increased the expression of CD44, a key stem cell marker, suggesting that there may be cross-talk between Notch-3 and CD44 to maintain the ovarian cancer stem cell phenotype." (PMID 40630953, 2025). "A recent analysis of the cancer genome atlas (TCGA) ovarian cancer data, largely comprised of HGSOC samples, has shown a significant reduction in DLL1, JAG1, NOCTH4, and an increase in HES1, NOCTH1 and NOTCH3 expression in OC samples compared to normal tissues." (PMID 40002854, 2025). "Indeed, given the Notch3 activation by COMP, we subsequently observed EMT induction in ovarian cancer cells following COMP treatment." (PMID 38615020, 2024). "Furthermore, Notch3 is known for maintaining cancer stem cell (CSC) markers and function in ovarian cancer including colony and spheroid formation, therapy resistance and in vivo tumorigenicity." (PMID 37815603, 2023). "In addition, NOTCH2, NOTCH3, DLL3, MAML1, and ADAM17 were determined as the five most relevant genes in ovarian cancer." (PMID 35136410, 2022). "In platinum/Taxane resistant ovarian cancer, Notch3 has been found to be upregulated, and downregulation of Notch3 by siRNA or GSI induces apoptosis in resistant cells." (PMID 33968932, 2021). "In ovarian cancer, researchers found that knockdown of BRD4 could significantly decrease Notch3 expression, and a chromatin immunoprecipitation test revealed that BRD4 existed in the promoter of Notch3." (PMID 34834420, 2021). "In summary, we have shown that the association of c-Kit with PHB upregulated phospho-PHBY259 in the lipid raft domain, resulting in subsequent activation of the Notch3—PBX1 and β-catenin—ABCG2 signaling pathways to increase stemness, tumorigenicity and drug resistance in ovarian cancer." (PMID 32169072, 2020). "Despite the strong evidence implicating NOTCH3 in ovarian cancer development, the role of Notch3 signaling in HGSC dissemination and progression is not well understood." (PMID 32525899, 2020). "We considered ID8 IP2 cells as a model with little evidence of Notch3 signal activation, and thus appropriate for determining the contribution of upregulated Notch3 signaling to ovarian cancer development." (PMID 32525899, 2020). "Notch3 mRNA high expression was not correlated to OS for all ovarian cancer patients HR, 0.92 (0.8–1.05), p = 0.2." (PMID 28415574, 2017). "Notch3 mRNA high expression was not correlated to PPS in ovarian cancer patients, HR 1.07 (0.9–1.28), p = 0.44." (PMID 28415574, 2017). "Taken together, the restoration of miR-150 induces the drug-resistant ovarian cancer cells to regain the sensitivity to PTX, and inhibits cancer cell migration and proliferation, at least partly by the repression of its target gene, Notch3, and its downstream proteins." (PMID 29069826, 2017). "Therefore, Notch3 expression and pS6 expression play important roles in PI3K/AKT/mTOR signaling and ovarian epithelial cancer development." (PMID 27445438, 2016). "The results indicate that the expression of Notch3 and pS6 was higher in ovarian epithelial cancer than in normal ovary tissues and in benign ovarian tumor tissues (p < 0.01)." (PMID 27445438, 2016).
ovarian carcinoma (continued). "In addition to demonstrating WWP2 as a regulator for Notch3 trafficking and signaling activity, this study has established a tumor suppressor role of WWP2 in ovarian cancer." (PMID 25356737, 2014). "In contrast, we did not observe a significant effect on the expression level of Notch3 by knocking down Jagged1, suggesting a “one-way” regulatory loop between Notch3 and Jagged1 in ovarian cancer cells." (PMID 20953350, 2010). "However, epithelial ovarian cancer is not known for the presence of any non-canonical form of Notch signaling; rather, the canonical Notch3 pathway is one of the major pathways responsible for promoting EOC." (PMID 35884426, 2022). "However, epithelial ovarian cancer is not known for the presence of any non-canonical form of Notch signaling; rather, canonical Notch3 pathway is a major pathway responsible for promoting EOC." (PMID 35884426, 2022). "While previous studies have shown that loss of Notch3 reduces cell survival in Notch3-overexpressing ovarian cancer, our results show that acquisition of Notch3 is not sufficient to increase survival, proliferation, or anchorage independent growth in these cells." (PMID 32525899, 2020). "Antibodies against the Notch ligand DLL4 have been tested clinically against tumor angiogenesis, but are unlikely to block Notch3 signaling, which appears to be activated by the ligand JAG1 in ovarian cancers where Notch3 signaling has not become ligand-independent." (PMID 32525899, 2020). "However, Notch3 mRNA high expression was not correlated to OS for all ovarian cancer patients HR, 0.92 (0.8–1.05), p = 0.2; Notch3 mRNA high expression was also not correlated to PPS in ovarian cancer patients, HR 1.07 (0.9–1.28), p = 0.44." (PMID 28415574, 2017). "Thus, despite reports of NOTCH1 PEST domain mutations in lung cancer and NOTCH3 amplification and acquired mutations in genes encoding other NOTCH pathway signaling components in ovarian cancer, NOTCH1 activation does not appear to be common in either of these tumors." (PMID 23825651, 2013). "Here, we surveyed the response of eight ovarian cancer cell lines to auranofin and found IC50 values ranging from 1.7 to 12 μM, with Notch3-negative SKOV3 cells having the highest IC50 value." (PMID 40985842, 2025). "An increase in Notch3 expression level and a decrease in WWP2 level were observed in ovarian cancer cell lines as compared to normal non-transformed epithelial cells." (PMID 25356737, 2014). "Using multiple approaches, including gene knockdown in ovarian cancer cells, ectopic expression in human OSE cells and induced Notch3 expression in mouse OSE and fallopian tube cells, we demonstrated that Notch3 signaling was essential and sufficient to upregulate Jagged1 expression." (PMID 20953350, 2010).